RAG1 (recombination activating 1)
Diseases named in the same sentence as RAG1 in open-access papers (continued):
Sharing a sentence is not in itself a finding about the gene and the disease.
Hypertension (14 papers, 2014 to 2024). The presence of chronic increased pressure in the systemic arterial system. "B and T lymphocytes cells are also linked to hypertension, as RAG1 and SCID mice that lack both the T and B cells, and BAFF-R mice, that lack mature B cells are protected from hypertension." (PMID 37266014, 2023). "For example, mice deficient in T and B cells due to genetic RAG-1 deficiency are resistant to hypertension induced by angiotensin II as well as other hypertension triggers." (PMID 29459637, 2018). "Genetic mutation of RAG1 in Dahl salt-sensitive rat, a hypertension model that can be induced by high salt diet, also attenuated HTN, but adoptive transfer of T cells can restore these cardiovascular abnormalities, indicating the crucial role of T cells in HTN-associated inflammation." (PMID 29118721, 2017). "While our initial studies using RAG1−/− mice have shown the pathogenetic role of T cells in this process, subsequent cooperation of numerous cells of the immune system, both innate and adaptive immunity, has been implicated in the development and maintenance of hypertension [1••, 2–7]." (PMID 31321561, 2019). "In a RAG-1–/– mouse model null of T and B lymphocytes, mice display a dampened form of hypertension, while reintroduction of T cells recapitulated the classical hypertension readouts." (PMID 33041853, 2020). "This study provided evidence that female RAG1−/− animals are protected from male T cell–mediated increases in hypertension when compared with male knockouts." (PMID 31321561, 2019). "The pro-hypertension role of CD8+ T cells was demonstrated in a CD8 deficient mouse model and adoptive transfer of T cells into immune-deficient Rag-1-/- mice." (PMID 26121471, 2015). "Alongside these broadened understandings of immune-mediated salt sensitivity, the contributions of T cells to hypertension have been recently challenged by groups whose findings did not support increased resistance of Rag-1-deficient mice to Ang II infusion." (PMID 38602583, 2024). "Some of the strongest evidence comes from RAG1−/− Dahl S rats, RAG1−/− mice and SCID mice (all models lack both T and B cells), which show a diminished rise in blood pressure in experimental hypertension." (PMID 39361560, 2024). "The Mattson lab demonstrated that the development of hypertension in Dahl S rats on a high salt diet was attenuated in Rag1 -/- Dahl S rats (lacking T and B cells) and CD247 -/- Dahl S rats (lacking functional T cells)." (PMID 39361560, 2024). "RAG1−/− mice have blunted hypertension and did not develop vascular pathologies during Ang II or deoxycorticosterone acetate (DOCA)-salt-induced hypertension." (PMID 31321561, 2019). "While all these studies were very informative, the direct proof of involvement of T cells in hypertension was provided by our studies in mice lacking recombination activating gene 1 (RAG1−/−), which was then confirmed in RAG1−/− Dahl salt-sensitive rats [1••, 32]." (PMID 31321561, 2019). "Although the results from the studies in Rag1-/- mice could not be repeated several years later (the discrepancy is thought to be due to genetic drift in the Rag1-/- strain), on the whole, there is still considerable evidence for a role of T cells in the development of hypertension." (PMID 39361560, 2024). "Work in mouse models has also confirmed a role for T cells in hypertension, an important contributor to vascular damage; RAG-1 double-knockout (RAG-1−/−) mice lacking both T cells and B-cells showed blunted hypertension in response to angiotensin-II infusion or (DOCA)-salt." (PMID 28303136, 2017).
lymphoma (14 papers, 2014 to 2025). A malignant (clonal) proliferation of B- lymphocytes or T- lymphocytes which involves the lymph nodes, bone marrow and/or extranodal sites. "We identified one homozygous founder RAG1 variant out of 24 available DNA samples from 71 patients who developed lymphoma aged <3 years from the Belarusian cancer registry between 1986 and 2023." (PMID 39026935, 2024). "A targeted screening program for searching the Slavic founder variant in RAG1 gene among Belarusian children who developed lymphoma aged <3 years revealed a 14-month-old Belarusian boy with low TREC levels who died of EBV-driven DLBCL and complications of chemotherapy including infections." (PMID 39026935, 2024). "The marked delay in lymphoma development seen in the Eμ-Myc;Rag-1-Cre;Mcl-1fl/+ mice suggested that Rag-1-Cre was considerably more efficient in Mcl-1fl deletion than CD19-Cre." (PMID 26962682, 2016). "To support this notion, we found that targeting Slfn2 by shRNA delayed lymphoma progression in Rag1−/− mice and prolonged their survival." (PMID 27206675, 2016). "Lymphoma-free survival was extended to a much greater extent in Eμ-Myc;Rag-1-Cre;Mcl-1fl/+ mice compared with the Eμ-Myc;CD19-Cre;Mcl-1fl/+ and Eμ-Myc;CD19-Cre;Mcl-1fl/fl animals." (PMID 26962682, 2016). "Relationship between quadruplexes and transposons can be seen in the cleavage of quadruplexes by RAG1 protein during translocations in human lymphomas because RAG1 protein evolved from transposase of the Transib family of DNA transposons." (PMID 25431265, 2014). "In particular, the RAG1/2 DNA recombinase induces somatic deletions and translocations in developing B- and T-lymphocytes, which sometimes dysregulates tumor suppressor and oncogenes, leading to malignant cell transformation and lymphoid cancer." (PMID 32411637, 2020). "To assess the oncogenic potential of BATF3 in lymphomagenesis and to dissect the molecular interactions of BATF3 in lymphoma cells, we retrovirally transduced murine mature T and B cells with a BATF3-encoding viral vector and transplanted each population into Rag1-deficient recipients." (PMID 29662618, 2018). "The lymphoma-burdened, sick Eμ-Myc;Rag-1-Cre;Mcl-1fl/+ mice showed significantly lower lymph node weights (*P=0.031) and lymphocyte numbers in the peripheral blood (*P=0.046) than sick Eμ-Myc;Rag-1-Cre mice." (PMID 26962682, 2016). "To test this hypothesis, we analyzed lymphoma cells from Eμ-Myc;Rag-1-Cre and Eμ-Myc;Rag-1-Cre;Mcl-1fl/+ mice for hCD4 expression." (PMID 26962682, 2016). "Remarkably, the median lymphoma-free survival of Eμ-Myc;Rag-1-Cre;Mcl-1fl/+ mice (346 days) was far longer than in control Eμ-Myc (91 days) and Eμ-Myc;Rag-1-Cre mice (129 days, P**=0.003), clearly demonstrating the importance of MCL-1 in c-MYC-induced lymphomagenesis." (PMID 26962682, 2016). "While kataegis and RAG1/2-mediated rearrangements have been observed in lymphoid malignancies in both children and adults, their developmental induction explains the peaking incidence of lymphoid leukemias and lymphomas in young children and adults that rapidly decreases with age." (PMID 32411637, 2020). "As the recipient Rag1-deficient mice lack polyclonal T cells and a normal architecture in lymph nodes and spleen, the lymphoproliferations can not be clearly linked to a specific type of human lymphoma in terms of the histological picture." (PMID 29662618, 2018). "In comparison to lymphomas infected with ΔEBNA2 alone, the ΔEBNA2 + Myc tumors have much higher expression of IGLL1 (CD179B, surrogate light chain), DNTT (terminal deoxynucleotidyltransferase, TDT), RAG1 and IL7R." (PMID 38620028, 2024).
lymphoma (continued). "Translocations proximal to non-consensus RSS-like sequences are frequently observed in lymphoid cancers expressing RAG1/2, but breakpoint junctions are not always precisely joined." (PMID 36370096, 2022).
Obesity (14 papers, 2012 to 2024). Accumulation of substantial excess body fat. "We evaluated the effects of orally administered B. uniformis on energy homeostasis, intestinal immunity, hormone levels, and gut microbiota in wild-type and Rag1-deficient mice with diet-induced obesity." (PMID 38845049, 2024). "Adoptive transfer of CD4+ T cells to T-cell-deficient Rag1−/− mice reduced obesity and improved diabetes." (PMID 23027613, 2012). "To test the impact of a hyperglycemic tumor microenvironments on OGT, we used B6.Rag1 knockout mice, an obesity-compatible mouse model, to measure effects in TNBC tumors." (PMID 37231419, 2023). "Nevertheless, mice with inactivating mutations in the recombination activating gene 1 (Rag1) backcrossed onto the C57BL/6 background, lack mature B and T lymphocytes, and yet, develop obesity, insulin resistance and hyperglycemia upon feeding a high-fat diet." (PMID 35533183, 2022). "In this study, Rag1-/- mice with high-fat diet-induced obesity and hyperinsulinaemia were subcutaneously implanted with PC3 prostate cancer xenografts to investigate the effect of UAG treatment on metabolic parameters and xenograft growth." (PMID 30458004, 2018). "We investigated whether obesity causes increased TNBC cell tumor initiation capacity and increased tumor MBD2_v2 expression using female B6.129S7‐Rag1tm1Mom/J (B6.Rag1−/−) mice as a model for DIO." (PMID 30636104, 2019). "The bacterium normalized insulin levels even in a background of Rag1-deficiency, but this effect was not sufficient to alleviate glucose intolerance, suggesting a defect in insulin signaling caused by systemic inflammation in obesity." (PMID 38845049, 2024). "The female Rag1−/−/MKR+/+ mice develop hyperinsulinemia but do not exhibit obesity, hyperglycemia or dyslipidemia." (PMID 31315653, 2019). "Depletion of CD8+ T cells in WT mice protects against obesity-induced IR, and the transfer of CD4+, but not CD8+ T cells, to Rag1–/– mice improves IR, suggesting that the CD4+/CD8+ T-cell balance is crucial for AT homeostasis." (PMID 32973799, 2020). "CD4+ T cells could be essentially involved as H2A−/− mice, which lack CD4+ T cells, did not develop an obesity memory and an accelerated weight regain occurred when CD4+ T cells of formerly obese mice were introduced to Rag1−/− mice." (PMID 32411095, 2020).
Stroke (13 papers, 2015 to 2024). Sudden impairment of blood flow to a part of the brain due to occlusion or rupture of an artery to the brain. "Differentiated T cells or vehicle were injected into the cisterna magna (CM) of lymphocyte-deficient Rag1−/− mice 24 hr after stroke." (PMID 36512388, 2022). "Importantly, Rag1−/− mice supplemented with T cells were fully susceptible to ischemic brain damage, proving that T cells are detrimental in early stroke development." (PMID 28576128, 2017). "Next, 2 × 106 transfected CD8+ T cells were injected via femoral vein to recipient Rag1−/− mice before the perioperative stroke model established." (PMID 35799259, 2022). "CD8+ T lymphocytes were transfected with lentivirus ex vivo to mobilize cell proliferation and differentiation before being transferred into recombination activating gene 1 (Rag1−/−) stroke mice." (PMID 35799259, 2022). "Using selective adoptive CD8+ T cells transfer into Rag1−/− mice in vivo, endogenous S-2HG reduction alleviates the ischemic brain injury and post-stroke cognitive dysfunction with fewer brain-infiltrating CD8+ T lymphocytes." (PMID 35799259, 2022). "Interestingly, platelets depletion in Rag1−/− mice that received an adoptive transfer of Treg cells reduces infarct size at the level as in naive Rag1−/− mice following tMCAO, thus underlining the decisive role of platelets in stroke-associated thromboinflammation." (PMID 35743029, 2022). "The cell distribution across condition highlighted that stroke is the main driver of the microglial transcriptomic changes, both in WT and Rag1−/− mice (right plot)." (PMID 36512388, 2022). "One million cells (TH1 or TREG cells) or vehicle (control, CT) were injected into the cisterna magna (CM) in Rag1−/− mice 24 hr after stroke induction (n=6 mice per condition)." (PMID 36512388, 2022). "Our results indicate that NK cells from Rag1−/− mice are fully functional and should therefore be considered in the interpretation of immune-cell transfer models in experimental stroke." (PMID 34105078, 2022). "The effect of PK136 treatment in both WT and Rag1−/− mice indicates a pivotal role of NK cells in stroke formation, which might bias cell subtype-specific analysis in Rag1−/− adoptive transfer experiments." (PMID 34105078, 2022). "To identify a more suitable mouse model for investigating immune cell subset-specific effects in stroke development, we used NRG mice carrying double genetic deficits in the Rag1 and the IL-2-receptor-γ-chain genes." (PMID 34105078, 2022). "Transient middle cerebral artery occlusion (60 min) was induced in wild-type mice treated with an anti-CD20 antibody 24 h before stroke onset, JHD−/− mice and Rag1−/− mice 24 h after adoptive B cell transfer." (PMID 28576128, 2017). "We also found that adoptive transfer of CD8+ TRLs reduced infarct volumes in Rag1-KO stroke mice without Teff transfer, indicating additional Teff-independent mechanisms of neuroprotection." (PMID 35912857, 2022). "In 2006, Yilmaz and co-workers first showed that Rag1−/− mice, i.e., animals lacking B and T cells, after adoptive transfer (AT) of T cells develop stroke volumes like wild-type (WT) animals, while Rag1−/− animals without AT are protected from IS." (PMID 28576128, 2017). "Adoptive transfer experiments of wild-type and K2P5.1−/− T lymphocytes into Rag1−/− mice prior to stroke induction showed no impact of K2P5.1 expression on T lymphocytes on stroke outcomes." (PMID 26213925, 2015). "Therefore, it is likely that NK cell development and functions are not altered in Rag1−/− mice and probably bias outcomes in stroke models." (PMID 34105078, 2022). "By comparing Rag1−/− mice reconstituted with B cells to Rag1−/− mice reconstituted with CD3+ T cells, studies have indicated that T cells likely have a vital effect on early stroke evolution and exert a detrimental effect as early as 24 h after stroke through an antigen-independent mechanism." (PMID 33461586, 2021).
primary immunodeficiencies (12 papers, 2008 to 2025). "RAG1 deficiency is a prototypical example of PID (Primary Immunodeficiency Diseases) with a wide range of phenotypic manifestations." (PMID 39720732, 2024). "Lastly, we performed an analysis of two example cases of abnormal B‐cell development caused by mutations in RAG‐1 and Wiskott–Aldrich syndrome gene in patients with primary immunodeficiency." (PMID 39235410, 2024). "Using a novel strategy of targeted resequencing a multitude of known primary immunodeficiencies genes in patients with predominantly antibody deficiency we identified compound heterozygous mutations in RAG1 or RAG2 in the two patients described." (PMID 26186701, 2015). "One vaccine challenge study was performed for each of the following strains of mice with a primary immunodeficiency: Stat4 KO, Ifngr KO, mut-Stat3, Dectin-1 KO, Rag-1 KO." (PMID 35071044, 2021). "We present the first application of our novel approach of predictive genomics using Recombination activating gene 1 (RAG1) and RAG2 deficiency as a model for a rare primary immunodeficiency (PID) caused by autosomal recessive variants." (PMID 31388879, 2019). "Novel computational framework tviblindi identifies branching B cell developmental trajectories in healthy (HD) and abnormal (RAG‐1 and Wiskott–Aldrich syndrome primary immunodeficiency) bone marrow and peripheral blood samples using 30 parameter mass cytometry." (PMID 39235410, 2024). "RAG1 and RAG2 mutations are reportedly frequent in multiple primary immunodeficiencies." (PMID 38240953, 2024). "Furthermore, several heterozygous variants were identified in genes associated with known primary immunodeficiencies that are inherited in an autosomal recessive manner, such as LYST, LRBA, RAG1, EXTL3, and STX11 (Group 4)." (PMID 30723478, 2018). "To validate this data, we investigated papers reporting the role of RAG1 and RAG2 in primary immunodeficiencies and their methylation status." (PMID 38240953, 2024).
diabetes (11 papers, 2012 to 2026). "Supporting the findings related to diabetes development, Rag1-/-KO mice also had significantly less severe insulitis compared to the Rag1-/-Ctr mice." (PMID 38903498, 2024). "Moreover, the incidence of diabetes in the Rag1-/-KO mice was significantly delayed and reduced compared with the Rag1-/-Ctr mice." (PMID 38903498, 2024). "Co-transfer of CD4+ and CD8+ T cells from NOD mice into Rag1−/− NOD mice upregulated the incidence of diabetes, whereas co-transfer of CD4+ and CD8+ T cells from IL-27rα−/− NOD mice into Rag1−/− NOD mice did not induce diabetes, demonstrating that IL-27 signaling is essential for T1D development." (PMID 38566992, 2024). "Our results show that DT administration into NOD.Rag1–/– recipients of splenocytes from cohorts of adult NOD.DEREG females promotes overt diabetes in all recipients, which correlated with an enrichment of effector/memory-type CD8+ T cells in the pLN but not scLN (data not shown)." (PMID 34447385, 2021). "After tolerogenic DEC-205+ dendritic cell vaccination to promote proinsulin-reactive Foxp3+ Treg cell activity, cotransfer of total spleen cells from autoimmune protected NOD donors can delay the onset of diabetogenic splenocyte-mediated diabetes in NOD.Rag1−/− recipients." (PMID 23691523, 2013). "Transferring splenocytes lacking ItgaL to NOD/Rag-1 experimental mice does not lead to the development of diabetes, which suggests that ItgaL has a role in NOD/LtJ T cell activation." (PMID 32938406, 2020).